AKT2 (AKT serine/threonine kinase 2)
Diseases named in the same sentence as AKT2 in open-access papers (continued):
Sharing a sentence is not in itself a finding about the gene and the disease.
oral cancer (5 papers, 2019 to 2025). "Oral cancer is characterized by several hallmark features amongst which up-regulation of Akt1 and Akt2 is considered significant." (PMID 38234400, 2023). "High-level expression of RAC-alpha serine/threonine-protein kinase (Akt1) and RAC-beta serine/threonine-protein kinase (Akt2) is responsible for oral cancer." (PMID 35251696, 2022). "Based on our investigations, it can be suggested that the selective inhibition of Akt1 or Akt2 isoforms would be a better approach for the management of oral cancer." (PMID 31252679, 2019). "It was found that the knockdown of Akt2 gene led to a reduction in the migration potential of oral cancer cells." (PMID 31252679, 2019). "The major goal of this pilot study was to see if SBVS could be used to find novel inhibitors with action against Akt1 and Akt2 in oral cancer." (PMID 35251696, 2022). "Thus, this study demonstrates that the identified lead compounds may act against Akt1 and Akt2 in oral cancer." (PMID 35251696, 2022). "In oral cancer, the silence of AKT1 and AKT2 inhibited the expression of COX-2, cyclinD1, and Bcl-2, which in turn inhibited cell survival." (PMID 36734243, 2023). "In pursuit of candidate/lead molecules for oral cancer, it is hypothesized that chemical entities inhibiting the overexpression of Akt1 and Akt2 without suppressing the expression of MAOB may demonstrate promising therapeutic potential." (PMID 38234400, 2023).
ovarian tumor (5 papers, 2011 to 2024). "In this report, we propose a potentially novel mechanism underlying NICTH involving stimulation of the insulin signaling pathway in a 58-year-old woman with a rare ovarian tumor of Müllerian origin that carries a duplication of the AKT2 gene." (PMID 35822150, 2022). "Ovarian tumor cells with an AKT1 knockdown show impaired tumor progression and metastasis, whereas an AKT2 knockdown leads to increased tumor progression and metastases formation." (PMID 31752925, 2019). "An interesting experiment has evaluated the function of SFRP5 in drug resistance in ovarian tumor; based on this experiment, epigenetic silencing of SFRP5 results in hyperactivation of Wnt to mediate EMT via TWIST upregulation and increases AKT2 levels in favor of drug resistance in ovarian tumor." (PMID 38334836, 2024). "Rictor was associated more with AKT1 rather than AKT2, and overexpression of Rictor facilitated IGF-1-induced AKT1 activation, whereas silencing of AKT1 but not AKT2 inhibited IGF-1- induced ovarian tumor cell migration." (PMID 22680924, 2012).
steatosis (5 papers, 2014 to 2018). Increased lipid within the cytoplasm of cells. "Our observations suggest that the effect of AKT2 on fibrogenesis is likely secondary to its role in steatosis and the subsequent liver injury." (PMID 27307790, 2016). "Deletion of FoxO1 in mouse liver results in steatosis while Akt2 deletion is protective for intracellular lipid accumulation that is induced by diet or Pten loss." (PMID 25502566, 2014). "In hepatocytes, PPARγ may play a predominant role in the metabolic adaptation downstream of PI3K/Akt2 pathway, leading to steatosis HBx also increases the expression of PPARγ, an effect thought to result from C/EBPα activation." (PMID 29183361, 2017).
/T-cell lymphoma (4 papers, 2016 to 2022). "It has indeed been shown that the miR-150 target gene repertoire can highly differ between different hematopoietic malignancies, e.g., MYB, FLT3, CBL and EGR2 in MLL-rearranged AML cells, and DKC1 and AKT2 in NK/T-cell lymphoma." (PMID 35205272, 2022). "MYB, FLT3, and EGR2 have been identified as critical target genes of miR-150 in MLL-rearranged AML, while AKT2 is a direct target of miR-150 in NK/T-cell lymphoma." (PMID 27917123, 2016). "Furthermore, luciferase reporter assays in NK/T cell lymphoma cells transfected with the AKT2 or AKT3 three prime untranslated region reporter constructs established AKT2 and AKT3 as direct targets of miR-150." (PMID 29386059, 2018).
endometrial cancer (4 papers, 2010 to 2016). Primary or metastatic malignant neoplasm involving the endometrium (mucous membrane that lines the endometrial cavity). "Mutations in AKT family members and their correlation with other gene alterations are found in endometrial carcinoma, including AKT2 (D399N), AKT2 (D32H) and AKT3 (E438D) mutations." (PMID 20368795, 2010). "In endometrial cancer cells, cisplatin increases Bcl-2 expression via activation of protein kinase C and Akt2." (PMID 25885284, 2015).
mammary adenocarcinomas (4 papers, 2015 to 2019). "However, recent investigations have now elegantly revealed the specific effects mediated by AKT1 and AKT2 isoforms in both the ErbB2-driven and the polyoma middle T (PyMT)-driven mammary adenocarcinoma transgenic mouse models." (PMID 29506489, 2018).
pancreatic ductal adenocarcinoma (4 papers, 2015 to 2020). An infiltrating adenocarcinoma that arises from the epithelial cells of the pancreas. "Inhibition of AKT2 activity reportedly increases the sensitivity of gemcitabine in human pancreatic ductal adenocarcinoma." (PMID 31514441, 2019). "In pancreatic ductal adenocarcinoma, miR-615-5p targetted AKT2 and inhibited AKT2-mediated cell proliferation." (PMID 30287504, 2018).
papillary thyroid carcinoma (4 papers, 2015 to 2022). "One study reported that hsa-let-7a inhibits migration, invasion, and tumor growth by targeting AKT2 in papillary thyroid carcinoma." (PMID 31963559, 2020). "Taken together, these findings suggest that let-7a acts as a novel suppressor by targeting the AKT2 gene and might be a candidate target for the development of novel therapeutic strategies to treat papillary thyroid carcinoma." (PMID 29050238, 2017). "A previous study showed that let-7a indeed repressed AKT2 expression in papillary thyroid carcinoma cells, yet our data showed no significant change in protein abundance upon let-7a transfection in HEK 293T cells." (PMID 35269443, 2022).
viral infection (4 papers, 2016 to 2022). "At day 3 of viral infection, we found that blocking Akt3, but not Akt1, Akt2, or Akt1 plus 2, resulted in an inhibition of colony growth and obvious floating, dead cells." (PMID 28483982, 2017).
aortic aneurysm (3 papers, 2015 to 2021). A ruptured aneurysm located in the wall of the proximal portion of the descending aorta proceeding from the arch of the aorta. "Akt2-deficient mice developed aortic aneurysm/dissection (AAD) after they had been stimulated with angiotensin II, and displayed inflammatory cell infiltration, apoptotic cell death, and tissue destruction in their aortas." (PMID 30925865, 2019). "For example, Akt2 appears to have a protective role in aortic aneurysm formation and dissection." (PMID 25929188, 2015). "Although we previously showed that AKT-2 plays a protective role in the aorta and identified decreased AKT-2 protein levels in sporadic aortic aneurysm tissue, in the present study we found no differential expression of AKT1 or AKT2 in SMCs or fibroblasts in MFS compared to controls." (PMID 35052435, 2021).
brain tumor (3 papers, 2012 to 2026). "In order to investigate the expression status of HBEGFand AKT2, as Hsa-miR-11181-5p target genes, RT-qPCR was applied for 16normal and brain tumour samples, including 6 GBM and 5 high-grade meningioma (grade IV)samples." (PMID 34455717, 2021). "Therefore, the expressions ofHBEGF and AKT2, as target genes ofHsa-miR-11181-5p, and TGFΒR1, as the target gene ofHsa-miR-11181-3p, were measured in brain tumour samples such as GBM andhigh-grade meningioma (grade IV)." (PMID 34455717, 2021).
diabetic retinopathy (3 papers, 2022 to 2025). "Recent reports also suggest that aberrant Akt2 signaling in RPE potentially contributes to retinal fibrosis in diabetic retinopathy." (PMID 41147690, 2025). "Consistent with our findings in the RPE of diabetic mice, reciprocal regulation of AKT1 and AKT2 phosphorylation in the RPE was observed in human diabetic retinopathy donor cadaver samples, compared to nondiabetic controls." (PMID 36229454, 2022).
familial partial lipodystrophy (3 papers, 2019). "This is the first report describing an in vitro endothelial cell model of AKT2 pathway dysregulation as in the disease familial partial lipodystrophy and in hypoinsulinemic hypoketotic hypoglycemia." (PMID 31835296, 2019).
gallbladder cancer (3 papers, 2016 to 2021). "Furthermore, elevated expression of H19 activated miR-194-5p targeting AKT2 gene expression by downregulating miR-194-5p and stimulated proliferation of gallbladder cancer cells by promoting cells into S-phase." (PMID 27738631, 2016). "AKT2, FGFR3, and FGF10 amplification had been reported in Chinese gallbladder carcinoma." (PMID 28029662, 2017).
head and neck squamous cell carcinoma (3 papers, 2021 to 2022). A squamous cell carcinoma that arises from any of the following anatomic sites: lip and oral cavity, nasal cavity, paranasal sinuses, pharynx, larynx, and salivary glands. "For example, CPSF1 promotes head and neck squamous cell carcinoma growth by regulating AS in cancer-associated genes, such as AKT2, HRAS, TGFBI, and UBE2C." (PMID 33748106, 2021). "For example, lncRNA LINC00460 enhances the progression of head and neck squamous cell carcinoma through sponging miR-612 and upregulating AKT2." (PMID 34621314, 2021).
invasive breast carcinoma (3 papers, 2017 to 2024). A carcinoma that infiltrates the breast parenchyma. "For invasive breast cancer the balance between Akt1 and Akt2 in combination with either high Twist or low miR200 and E-cadherin expression seems to be relevant for the development of an EMT-like phenotype." (PMID 38291468, 2024). "In invasive breast carcinoma, CD44v6 is explicitly expressed on luminal epithelial cells, whereas AKT2 is present in the epithelial and stromal compartments in a similar ratio." (PMID 36532641, 2022). "Finally, we found, in a univariate analysis of 1105 samples of breast invasive cancer from TCGA, that patients that carry mutations that increase abundance of AKT1 mRNA level have a better outcome than patients with mutations at the level of AKT2, who have shorter overall survival." (PMID 28287129, 2017). "Furthermore, we evaluated The Cancer Genome Atlas (TCGA) dataset for invasive breast carcinomas and found that increased AKT2 but not AKT1 mRNA levels correlated with a worse clinical outcome." (PMID 28287129, 2017).
lymph node metastasis (3 papers, 2015 to 2021). "Another family member, Let-7a, was found to negatively regulate the expression of lin28 and AKT2 genes and via the c-myc pathway is associated with TNM stage, lymph node metastasis, and recurrence." (PMID 35186709, 2021). "Using this cellular model, we demonstrated that stable silencing of Akt2 had no impact on the incidence of LNM35 lymph node metastasis but led to the inhibition of their growth (13.3 mg +/−3.37 in the Akt2-shRNA group in comparison with 27.4 mg +/−8.54 in the control-shRNA group)." (PMID 26234648, 2015).
malignant glioma (3 papers, 2014 to 2024). A grade III or grade IV glioma arising from the central nervous system. "In malignant glioma, the AKT2-specific phosphorylation of PDHK1 at Thr346 was shown to increase the phosphorylation of PDHE1α." (PMID 37894325, 2023).
meningioma (3 papers, 2020 to 2024). A generally slow growing tumor attached to the dura mater. "In meningiomas, AKT2 expression is negatively correlated with patient recurrence-free survival." (PMID 32873299, 2020).
osteoporosis (3 papers, 2019 to 2023). A condition of reduced bone mass, with decreased cortical thickness and a decrease in the number and size of the trabeculae of cancellous bone (but normal chemical composition), resulting in increased fracture incidence. "Fusobacteria have been shown to promote M1 macrophage production via AKT2 signaling, which induces inflammation and has been associated with the development of osteoporosis." (PMID 35372129, 2022). "Fusobacteria has been shown to promote M1 macrophage production via AKT2 signaling, which induces inflammation and prompts the development of osteoporosis." (PMID 37077242, 2023).
partial lipodystrophy (3 papers, 2016 to 2021). Loss and redistribution of subcutaneous and/or visceral adipose tissue from specific regions of the body. "Of the 9 patients, 4 had a proven INSR variant, 4 had partial lipodystrophy (3 associated with known genetic variants), and 1 had a heterozygous pathogenic variant in AKT2 (previously reported in 4, 17, 20-29)." (PMID 33901270, 2021). "In addition, a missense mutation in the akt2 gene, which renders the Akt2 protein dominant-negative, was identified in a family that showed dominant inheritance of severe insulin-resistant diabetes, and the proband of this family had partial lipodystrophy." (PMID 34639094, 2021).
psoriasis (3 papers, 2020 to 2022). An autoimmune condition characterized by red, well-delineated plaques with silvery scales that are usually on the extensor surfaces and scalp. "Moreover, BCAA supplementation suppresses Akt2 activation through mTORC1- and mTORC2-dependent pathways 44, and NF-κB and mTOR are therapeutic targets of psoriasis." (PMID 33391503, 2021). "AKT2 participates in the PI3K/AKT/mTOR signaling pathway as a critical mediator in psoriasis." (PMID 32411787, 2020). "Fisetin treatment was also shown to decrease the expression of Akt2 mRNA and DEFB4A, a key contributor to the pathophysiology of psoriasis." (PMID 36741386, 2022).
pulmonary fibrosis (3 papers, 2019 to 2024). Chronic progressive interstitial lung disorder characterized by the replacement of the lung tissue by connective tissue, leading to progressive dyspnea, respiratory failure, or right heart failure. "Deficiency of AKT2 can inhibit bleomycin-induced pulmonary fibrosis and inflammation." (PMID 39479511, 2024). "Akt2-deficient mice are protected against bleomycin-induced pulmonary fibrosis and inflammation." (PMID 31527305, 2019). "While there are three isoforms (AKT1, AKT2, and AKT3), researches related to pulmonary fibrosis have predominantly focused on the AKT1 and AKT2 isoforms." (PMID 39479511, 2024).
renal carcinoma (3 papers, 2015 to 2025). A carcinoma arising from the epithelium of the renal parenchyma or the renal pelvis. "Inhibition of Akt2 expression by siRNA enhanced the sensitivity of renal cancer cells to 5-FU." (PMID 25951903, 2015).
renal cell carcinoma (3 papers, 2019 to 2025). "In renal cell carcinoma, let-7b overexpression suppresses AKT2, enhances apoptosis, and increases sensitivity to 5-fluorouracil (5-FU)." (PMID 41303548, 2025). "It was also found that miR-148a could suppress human renal cell carcinoma malignancy by targeting AKT2." (PMID 31455210, 2019).
renal fibrosis (3 papers, 2014 to 2020). A final common manifestation of a wide variety of chronic kidney diseases characterized by glomerulosclerosis and tubulointerstitial fibrosis. "All the fibrogenic hallmarks of renal fibrosis were attenuated in the obstructed kidneys from the Akt2 KO mice, including the less of fibronectin and collagen I accumulation." (PMID 25148525, 2014). "Indicating that Akt2 is involved in the development of renal fibrosis." (PMID 25148525, 2014). "Our findings suggest that Akt2 partially contributes to interstitial fibrosis following UUO and that inhibition of this signaling pathway may provide a novel approach of prevent progression of renal fibrosis." (PMID 25148525, 2014). "In previous in vitro study, we found that Akt2 activity is involved in TGF-β1-induced EMT in HK-2 cells, but whether Akt2 activity is involved in renal tubular EMT and renal fibrosis in vivo has not been reported." (PMID 25148525, 2014).
SHORT syndrome (3 papers, 2016 to 2022). A rare disorder characterized by multiple congenital anomalies, including short stature, hyperextensibility of joints, ocular depression, Rieger anomaly and teething delay in which the cause of the disease is a mutation in PIK3R1 gene. "Hereditary insulin resistance syndromes include genetic syndromes caused by INSR mutations, SHORT syndromes caused by PIK3R1 abnormalities, and conditions caused by AKT2, TBC1D4, or PRKCE abnormalities." (PMID 36626508, 2022).
type I diabetes (3 papers, 2008 to 2019). "Interestingly, we observed increased phosphorylation of Akt2 in the glomeruli of rats with type 1 diabetes." (PMID 30444896, 2018).
bipolar disorder (2 papers, 2012 to 2022). A disorder of the brain that causes unusual shifts in mood, energy, activity levels and the ability to carry out day-to-day tasks. "The expression of AKT-2 is low in patients with bipolar disorder and may be linked to electrophysiological disfunctions observed in patients with this diagnosis." (PMID 35203296, 2022).
carcinosarcoma (2 papers, 2017 to 2022). A malignant tumor composed of a mixture of carcinomatous and sarcomatous elements. "Carcinosarcomas had targetable mutations in AKT2 and harbored a resistance mutation in ESR1." (PMID 28424409, 2017). "A PDZD2-AKT2 fusion detected in sample AF0162, which was diagnosed as carcinosarcoma, was excluded because the intronic fusion led to out-of-frame to eliminate the function of AKT2 and low read counts (<10)." (PMID 36033527, 2022).
cardiac ischemia (2 papers, 2017 to 2021). "Several studies have found that AKT2 gene knockout mice have more severe cardiomyocyte apoptosis than normal mice during myocardial ischemia, indicating that AKT2 also has a role in reducing cardiomyocyte apoptosis and protecting the heart." (PMID 34084134, 2021). "Our data demonstrate that AKT2 inhibition induces the silencing of caspase activation which mediates both FADD (Fas-associated death domain)- and mitochondrial-dependent apoptosis during cardiac ischemia." (PMID 28272306, 2017). "Our results show that cytosolic translocation of Cyto C is in parallel with MOMP elevation, which strengthens our conclusion that mitochondrial permeabilization is disrupted by AKT2 inhibition during cardiac ischemia, and the release of mitochondrial Cyto C is a precedent of mitochondrial injury." (PMID 28272306, 2017). "As shown in our data, increased apoptosis was observed in ischemic cardiomyocytes compared with control; suppressed AIF or EndoG expression correlates with a significant reduction of DNA damage to nearly the same level as cardiomyocytes only treated with AKT2 inhibitor during cardiac ischemia." (PMID 28272306, 2017). "Our results show that AKT2 inhibition induces a unique mitochondrial-dependent DNA degradation pathway by activating nucleus translocation of AIF and EndoG during cardiac ischemia, suggesting a new function and mechanism of AKT2 in regulating cardiomyocyte survival." (PMID 28272306, 2017).
clear-cell ovarian cancer (2 papers, 2015 to 2025). "Activating mutations in PIK3CA have been described to occur in 33–40% of clear-cell ovarian cancer, and loss of PTEN expression has been found in 40% of clear-cell ovarian cancers and AKT2 amplification in 14%." (PMID 26413541, 2015).
COVID-19 (2 papers, 2023). A disease caused by infection with severe acute respiratory syndrome coronavirus 2. "Comparative analysis of two peptides has shown that they have common binding sites in the AKT1 and AKT2 genes, the protein products of which are functionally associated with the development of the cytokine storm in COVID-19." (PMID 37686182, 2023). "The presence of AKT3, as well as its isoform AKT2, in our list of prioritized targets supports the predicted association of the PI3K/AKT signaling pathway with COVID-19 as observed in our analysis of the bulk RNA datasets." (PMID 37137934, 2023).
enteroviral infection (2 papers, 2014 to 2016). "The study used pharmacological inactivation of Akt by Akt1/Akt2 inhibitor and this led to increased enteroviral infection." (PMID 25412347, 2014).
esophageal cancer (2 papers, 2023 to 2024). A primary or metastatic malignant neoplasm involving the esophagus. "In specifically, circ-RAD23B regulates PARP2 and AKT2 by sponging miR-5095 in esophageal cancer." (PMID 38289973, 2024).